CXCL10 (C-X-C motif chemokine ligand 10)
Diseases named in the same sentence as CXCL10 in open-access papers (continued):
Sharing a sentence is not in itself a finding about the gene and the disease.
glioma (continued). "Additionally, CXCL10 levels were notably higher in glioma tissues compared to normal tissues." (PMID 38461458, 2024). "In gliomas, the IDH1 mutation has a negative impact on the immune system resulting in reduced Natural Killer ligands and decreased tumor lysis, as well as decreased chemokines CXCL9, CXCL10 with subsequent reduction in the number of CD3+ CD8+ tumor infiltrating lymphocytes." (PMID 35664748, 2022). "In conclusion, our findings suggest that downregulation of the CCL2/CCR2 and CXCL10/CXCR3 axes via inhibition of the NF-κB pathway in the tumor and the tumor microenvironment might have contributed to the antitumor effects of celecoxib observed in the mouse glioma model." (PMID 32943658, 2020). "Taken together, these results indicate that reduced astrocytic Cxcl10 expression in glioma-bearing mouse strains likely reflects an absence of CD4 T cells, which induce Cxcl10 expression in astrocytes to hinder LGG growth in vivo." (PMID 35986378, 2022). "We newly found that in the mouse glioma model, celecoxib decreased mRNA levels of Ccl2, CxcL10 and Cxcr3 but not of Ccr2 and protein expression of CCL2 and CXCL10 in the tumor and peri-tumor." (PMID 32943658, 2020). "Each disease group of the non-infectious CNS disorders independently showed IP-10/CXCL10 levels that are significantly lower than the infection group [(autoimmune /demyelinating disorders (p = 0.0005), lymphomas (p = 0.0487), gliomas (p = 0.0294), and controls (p = 0.0001)]." (PMID 30379898, 2018). "Importantly, a subset of these human-derived cytokines that included CXCL10, IL-33, CXCL8, KITLG, CCL2, and TGFα were not secreted or secreted at very low levels in vitro by BT147 cells, suggesting that the increased secretion was the result of a glioma–host cell interaction within the brain." (PMID 33020472, 2020).
colorectal cancer (86 papers, 2012 to 2025). A primary or metastatic malignant neoplasm that affects the colon or rectum. "DNA mismatch repair-deficient colorectal cancer cells can overexpress CXCL10 and CCL5 via endogenous activation of type I interferon signaling, thus increasing the recruitment of CD8+ T cells into tumors." (PMID 38762546, 2024). "Clinically, CXCL10 been associated with pro- and anti- tumour responses in colorectal cancer patients." (PMID 35226704, 2022). "Both CXCL8 and CXCL10 are chemoattractants that have been implicated in colorectal cancer progression." (PMID 28717003, 2017). "A recent study across 3,763 colorectal cancer patients suggested lower CXCL10 expression was significantly associated with disease spread, recurrence and overall survival, and this association was dependent on other factors such as age and population-based genetic differences." (PMID 35226704, 2022). "KRT17 is upregulated in mismatch repair-deficient colorectal cancer, where it enhances T cell infiltration via the YTHDF2/CXCL10 signaling axis, thereby reversing immune evasion." (PMID 40986143, 2025). "Studies have consistently shown that high levels of CXCL9 and CXCL10 in the TME are associated with greater CD8+ TIL density and improved survival in ovarian, breast, and colorectal cancers." (PMID 40475782, 2025). "In this study, we characterized the colorectal cancer landscape using single-cell data and discovered that CXCL10 is highly expressed in M1 macrophages." (PMID 39170612, 2024). "Previous studies have reported the association between STAT1 and CXCL10 in PDAC and colorectal cancer." (PMID 37156839, 2023). "The expression levels of VSIG4, ZNF532, MEIS2, and CXCL13 were downregulated, while CXCL10 was elevated between colorectal cancer and normal tissues." (PMID 36909170, 2023). "TNF-α promotes epithelial-–mesenchymal transition by stimulating the CXCL10/CXCR3 axis of colorectal cancer cells." (PMID 37048082, 2023). "In this study, we conducted differential gene expression analysis on three GEO datasets and confirmed SPP1, MMP1, CXCL8, CXCL1, TIMP1, MMP3, and CXCL10 as core regulatory genes in colorectal cancer through a protein-protein interaction network." (PMID 37842645, 2023). "This regulation occurs in part through the control of Th1-type chemokines, such as chemokine (C-X-C motif) ligand 9 (CXCL9) and CXCL10, which regulate effector T-cell recruitment to the colorectal cancer microenvironment." (PMID 34385592, 2022). "Elevated levels of CXCL10 in the serum of patients with colorectal cancer correlated with liver metastasis and poor survival." (PMID 36498469, 2022). "In colorectal cancer, KRAS mutation suppresses Th1/CTL immunity, reducing IFNγ and CXCL10 production, therefore decreasing CTL infiltration." (PMID 36311166, 2022). "Conversely, ARID1A (BAF250A), a core member of the SWI/SNF complex, supports CXCL9 and CXCL10 expression in human colorectal cancer cells, resulting in enhanced recruitment of IFNγ-producing immune cells." (PMID 34385592, 2022). "Further, some studies have found that CXCL10 can exert tumor inhibition by inhibiting angiogenesis in colorectal cancer, lung cancer, cervical cancer, and other tumors." (PMID 34794429, 2021). "Our result showed that high expression of CXCL9 and CXCL10 were correlated with a better prognosis, which is consistent with studies of colorectal cancer in recent years." (PMID 35251116, 2021). "Recently, some researchers have taken a different approach and investigated the direct effects of CXCL10 on tumor-promoting functions in colorectal carcinoma cells." (PMID 34422627, 2021). "Neuroendocrine-like cell-derived CXCL10 and CXCL11 induce the infiltration of tumor-associated macrophages and lead to the poor prognosis of colorectal cancer." (PMID 32337262, 2020). "Secretion of CXCL10 and CCL5 in the tumor has been associated with accumulation of granzyme producing CD8+ and IFN-γ producing CD4+ T cells in colorectal carcinomas, and early TNM staging." (PMID 32033490, 2020).
colorectal cancer (continued). "CXCL10 and CXCL11 were also associated with poor prognosis in a model for colorectal cancer by initiating macrophage infiltration." (PMID 29379506, 2017). "Consistent with our observations, CCL5 and CXCL10 are reported to recruit antitumor CD8+ T lymphocytes into malignancies and are positively associated with the survival of patients with colorectal cancer or hepatocellular carcinoma." (PMID 26317795, 2015). "CXCL10 is constitutively expressed in normal human colonic epithelium and was shown to be elevated as well as suppressed in colorectal cancer (CRC) compared to adjacent normal tissue." (PMID 24748971, 2014). "This is consistent with the recent finding that CXCR3 and another ligand CXCL10 promote invasion-related properties in colorectal cancer." (PMID 22438977, 2012). "CXCL10 secreted from CXCR3-expressing colorectal carcinoma cells promotes, by an autocrine mechanism, some progression-promoting functions in these tumor cells." (PMID 22408433, 2012). "The infiltrating Th1 cells secrete IFNγ, which, in addition to its immune functions, promotes the release of CXCL10 from IFNγ receptor-expressing colorectal carcinoma cells while up-regulating CXCR3 expression." (PMID 22408433, 2012). "CXCL10 has been shown to promote invasion-related properties of colorectal carcinoma cells, and it also regulates angiogenesis." (PMID 22427941, 2012). "This further promotes the capacity of the colorectal carcinoma cells to respond to CXCL10-mediated promalignancy functions." (PMID 22408433, 2012). "Notably, endogenous STING signaling upregulates CXCL10 and CCL5 in mismatch repair-deficient colorectal cancers, facilitating dense CD8+ T cell infiltration." (PMID 40475782, 2025). "Moreover, the deletion of METTL3 or METTL14 increases the infiltration of cytotoxic CD8+ T cells and the secretion of the cytokines IFN-γ, CXCL9, and CXCL10, thereby improving the response to anti-PD-1 therapy in colorectal cancer." (PMID 40986143, 2025). "In addition, CXCL10 can also promote vascular normalization and increase the sensitivity of colorectal cancer to cetuximab combined with PD-1 checkpoint inhibitors." (PMID 39399504, 2024). "Transcriptional profiling of human colorectal cancer (CRC) tissues revealed that active secretion of CCL5 and CXCL10 from the tumor microenvironment is closely associated with GZMB + CD8+ T cell infiltration, suggesting a critical role of CCL5 and CXCL10 in CTL recruitment." (PMID 35292660, 2022). "This suggests that CXCL10 expression may have potential as a predictive biomarker in colorectal cancer management, once these variables are taken into account." (PMID 35226704, 2022). "Moreover, a recent study has revealed that CCL5 and CXCL10 expressed by colorectal cancer tissues promote the migration of GrzB+ CD8+ T cells." (PMID 30984181, 2019). "Low expression of CXCL10 has been previously associated with survival in stage II and III colorectal cancers and it could be used as a marker to better characterize high risk patients and maximize the benefits of adjuvant therapy." (PMID 26359356, 2015). "One such chemokine, CXCL10, was found to be expressed in colorectal cancer (CRC) tissue." (PMID 24748971, 2014). "Recent studies in mouse models of colorectal cancer have shown that IL-17 inhibits the production of the chemokines CXCL9 and CXCL10 by tumor cells, reducing the recruitment of CD8+ T cells." (PMID 41383591, 2025). "Western blot analysis confirmed the increased expression of IFN-β and CXCL10 as well as phosphorylation of TBK1, IRFs, and STAT1 in FGFR4-overexpressing colorectal cancer cells." (PMID 40447617, 2025). "Chemokines, including CXCL10, CXCL12, CX3CL1, CCL2, CCL5, CCL18, and CCL20, induce chemotaxis to promote cell migration and invasion in ovarian, lung, breast, and colorectal cancers." (PMID 38438872, 2024).
colorectal cancer (continued). "For this reason, we screened 7 m6A-related genes (IL12RB1, FASLG, CXCL13, GBP2, CXCL10, CXCR6, and CIITA) through WGCNA and LASSO regression in this study and established an m6A-GPI in colorectal cancer." (PMID 37427112, 2023). "For example, in colorectal cancer high levels of CXCL9 and CXCL10 correlated with increased disease-free survival." (PMID 29379506, 2017). "Our finding showed that CXCL10 and CXCL11 play important roles in the interaction of neuroendocrine differentiation and TAMs and the poor prognosis of colorectal cancer." (PMID 27034164, 2016). "Therefore, we investigated the expression of PD-L1, ICAM-1, CXCL10, and IFNs-mediated ISG15 expression in patients with lung cancer (LUAD), liver cancer (LIHC), and colorectal cancer (COAD) using the available GEPIA based on the TCGA database." (PMID 38953994, 2024). "The relationship between CXCL10 and DDIR score is also observed in advanced colorectal cancer." (PMID 38744099, 2024). "In addition, CXCL10 is reported as a member of a 12-cytokine gene signature to predict TLS and patient survival in colorectal cancer." (PMID 37348499, 2023). "CXCL9, CXCL10, CXCL11/CXCR3 axis has been proved to regulate immune cell migration, differentiation, and activation, leading to tumor suppression in pancreatic adenocarcinoma, colorectal cancer and so on." (PMID 34777466, 2021). "Sato E had verified CXCL10 was an inhibitor to growth and metastases in tumor, and different expression level in CRC patients had different prognostic In Jessicca D. Abron’s study, he investigated the role of CXCR3 in inflammation and colorectal cancer." (PMID 30973890, 2019). "Therefore, we evaluated the contribution of the CXCR3-ligands CXCL9, CXCL10 and CXCL11 to colorectal carcinogenesis by analysis of their expression and prognostic relevance in human colorectal cancer tissue." (PMID 29163806, 2017). "Interestingly, high expression levels of CXCL9 and CXCL10 in colorectal cancer samples correlated with T cell infiltration, but not with NK cell infiltration that was scarce in the analyzed samples." (PMID 30319622, 2018). "However, we failed to observe effects on cell migration by addition of CXCL10 in colorectal cancer cell lines of mouse or human origin." (PMID 29163806, 2017).
Sepsis (81 papers, 2010 to 2025). Sepsis is defined as life-threatening organ dysfunction caused by a dysregulated host response to infection. "Prior research has indicated that increased amounts of Cxcl10 are linked to different inflammatory conditions, such as sepsis, where it worsens the inflammatory environment." (PMID 40792069, 2025). "Specific pro-inflammatory cytokines, including IL-1β, CCL4, CCL5, and CXCL10, have emerged as potential diagnostic markers for sepsis and critical indicators of cytokine storm severity." (PMID 38496165, 2024). "IFNAR blockade by anti-IFNAR antibodies decreased the LPS-induced upregulation of mRNA encoding several ISG, including Cxcl10, which targets Th1 lymphocytes and is involved in sepsis-associated kidney injury and other kidney disease conditions." (PMID 36386242, 2022). "Other studies have identified the use of IL-1β, CCL4, CCL5 and CXCL10 as possible diagnostic markers for sepsis." (PMID 35811678, 2022). "Punyadeera and colleagues showed that high plasma CXCL10 concentrations are associated with the transition from sepsis to septic shock in critically ill adult patients." (PMID 24890566, 2014). "In mice models, better survival with less bacterial burden in the lungs and blood was shown in CXCL10-deficient mice, suggesting that CXCL10-targeted treatments might be promising approaches for acute sepsis." (PMID 40076848, 2025). "Sepsis-induced hypothermia and systemic cytokine production were attenuated and survival rates were higher in CXCL10-deficient mice and in mice treated with a neutralizing antibody against CXCL10, compared to control mice." (PMID 24890566, 2014). "Plasma levels of IL‐12, IL‐15, TNF, IFNγ and CXCL10 correlated with the magnitude of MAIT cell activation in sepsis patients." (PMID 40041474, 2025). "Cxcl10, Il6, and Stat1 showed higher levels of expression in the sepsis group than in the control group in the RNA-seq data (P < 0.05)." (PMID 40792069, 2025). "In the sepsis group, there was a notable increase in the expression of Cxcl10, Il6, and Stat1, which aligns with the findings from the RNA-seq data." (PMID 40792069, 2025). "In the validation set GSE209706, the sepsis (LPS-treated) group showed significantly increased levels of Cxcl10, Il6, and Stat1 compared to the control group." (PMID 40792069, 2025). "Specifically, we report here that CLP-sepsis caused a significant increase in IL-1β, IL-6, CCL3, CLL4, CXCL1, CXCL10 and GM-CSF, all of which contribute to sepsis-induced cytokine storm and, hence, to cardiac and organ dysfunction." (PMID 39559354, 2024). "Hepatic sinusoidal endothelial cells in the affected liver inhibit NK cell infiltration in tissues after CXCL10 knockout in a sepsis model." (PMID 38494504, 2024). "Pro-inflammatory cytokines, including interleukin-1β (IL-1β), CCL4, CCL5, and CXCL10, have emerged as potential biomarkers with significant implications for diagnosing sepsis and assessing the severity of cytokine storms." (PMID 38496165, 2024). "For cytokine profiles, the levels of both proinflammatory (such as IL-6, GM-CSF, and CXCL10) and anti-inflammatory (such as IL-1ra, IL-10, and PD-L1) cytokines were increased in bacteremia and sepsis patients compared to HCs." (PMID 38707899, 2024). "Regarding neutrophils, the levels of Tnfα, IL-6, IL-1β, CXCL1, CXCL2, CCL5, and CXCL10 increased significantly in response to sepsis sEVs compared with those from the control group and healthy individuals." (PMID 38910259, 2024). "Among the extensive crosstalk across these major subtypes, KC_Cxcl10 shared strong potential interaction with other cells when responding to sepsis." (PMID 37808269, 2023). "Simultaneously, enhanced interaction between KC_Cxcl10 and Neu subtypes through chemokine ligands and receptors such as Ccl5–Ccr1 indicated increased chemotaxis from KC_Cxcl10 to Neu during sepsis." (PMID 37808269, 2023).
Sepsis (continued). "This increase which was the largest among all compared subsets highlighted the potential capability of KC_Cxcl10 cells to respond to sepsis." (PMID 37808269, 2023). "In parallel, CXCL10 protects moderate sepsis but aggravates tissue injury and mortality in severe septic shock induced by cecal ligation and puncture." (PMID 39619227, 2023). "Levels of MIP1-β/CCL4, RANTES/CCL5 and IP10/CXCL10 were significantly lower in children with sepsis when compared to children with malaria (p<0.01), but was higher when compared to febrile controls (p<0.01)." (PMID 35811678, 2022). "Prior studies have also shown that CXCL10 has predictive ability for sepsis in human adults, infants and neonates." (PMID 34481469, 2021). "PC2iNTS is characterized by a cytokine profile typically described in patients with sepsis, with concomitantly raised proinflammatory (IL-6, IL-8, CXCL10, and IL-15) and anti-inflammatory (IL-10 and IL-1Ra) cytokines." (PMID 27170644, 2016). "Based on our current observations, immunoglobulin-based strategies appear to represent an attractive strategy for blocking CXCL10 in the setting of severe sepsis." (PMID 24890566, 2014). "The mechanisms by which CXCL10 facilitates systemic inflammation and physiologic dysfunction during severe sepsis remain to be fully ascertained." (PMID 24890566, 2014). "Elevated plasma CXCL10 concentrations have also been shown to be a reliable indicator of sepsis in neonates and infants." (PMID 24890566, 2014). "In clinical studies, plasma CXCL10 concentrations are markedly elevated in septic patients and plasma CXCL10 concentrations correlate with the severity of sepsis in humans." (PMID 24890566, 2014). "STAT1 knockout mice exhibited improved survival, attenuated systemic inflammation and diminished CXCL10 production during CLP-induced sepsis." (PMID 24890566, 2014). "In toto, these combined findings indicate that CXCL10 production can be beneficial or deleterious depending on the severity of sepsis." (PMID 24890566, 2014). "In other studies, elevated plasma CXCL10 concentrations have been shown to be a reliable indicator of sepsis in neonates and infants." (PMID 24890566, 2014). "High levels of CXCL10 have been observed in the plasma of septic patients, and plasma CXCL10 concentrations have been shown to parallel the severity of sepsis in humans." (PMID 22992408, 2012). "Punyadeera and colleagues showed that increasing plasma CXCL10 concentrations were predictive of progression from sepsis to septic shock in critically ill patients." (PMID 22992408, 2012). "Furthermore, functional experiments demonstrated that suppression of SFT2D1 significantly reduced the expression of inflammatory cytokines CXCL10 and IL-6, suggesting its potential role in modulating the inflammatory response in sepsis." (PMID 40370519, 2025). "The top ten differentially expressed genes in this study include Gm29879, Lcn2, Cxcl10, Zbp1, Lbhd2, C5aR1, Cxcl10, Lbhd2, Cxcl9, and Fpr1, all of which might play a role in the pathophysiology of sepsis-induced WMI." (PMID 41584453, 2025). "Taken together, it appears that mutual regulation among KC_Cxcl10, Endo cells, Hep and Neu could escalate the inflammation response into a cytokine storm during sepsis." (PMID 37808269, 2023). "Some studies have shown that the levels of characteristic cytokines such as TNF‐α, IL‐6, IL‐1β, IL‐1α, IL‐12, IL‐17, CXCL1, CXCL2, MCP‐1, IL‐8, CXCL10, GM‐CSF, M‐CSF, and G‐CSF in patients with septicemia are significantly higher than those in normal volunteers." (PMID 36684101, 2023). "In addition, we observed broad interactions between KC_Cxcl10/KC_Cd5l and Hep/Endo through chemokines (including Cxc and Cc subfamilies) and the receptor Ackr1 in response to sepsis." (PMID 37808269, 2023). "Importantly, the levels of CCL4, CCL5 and CXCL10 have been reported to be increased in both sepsis and malaria." (PMID 35811678, 2022).